ALK (ALK receptor tyrosine kinase)
Diseases named in the same sentence as ALK in open-access papers (continued):
Sharing a sentence is not in itself a finding about the gene and the disease.
lymphoma (continued). "We analyzed whole-exome sequencing (WES) data of lymphoma and matched non-tumoral tissue from 27 ALK + ALCL patients, using an internally developed pipeline." (PMID 39478125, 2024). "Furthermore, recent progress in basic and translational research has improved treatment options for lymphoma, including FDA-approved crizotinib for ALK-positive ALCL and Brentuximab Vedotin for CD30-positive T-cell lymphoma." (PMID 38365716, 2024). "Moreover, ALK protein was found to be immunogenic in humans, and patients with ALK-driven lymphoma and NSCLC are known to spontaneously develop a natural immune response against ALK protein." (PMID 39767726, 2024). "ALK negative ALCL nodal lymphomas have all the other morphological and phenotypical features of a CD30 positive cytotoxic ALCL, except ALK expression." (PMID 37188189, 2023). "ALK is a lymphoma marker, and, as it is negative, there are questions regarding the classification of BIA-ALCL as a true lymphoma." (PMID 37780912, 2023). "Finally, for T-cell NHL (8% of the lymphoma cases), one case (ALCL CD30+/ALK+) had submandibular lymph node involvement as well as diffuse abdominal involvement (spleen, small intestine, and mesenteric lymph nodes)." (PMID 36551614, 2022). "Regarding lymphomas, IRS-1 has been demonstrated to activate anaplastic lymphoma kinase (ALK), which is involved in ALCL, and IRS-4 could mediate the mitogenic signaling of LB cells: a murine pre-T-cell lymphoma." (PMID 36555171, 2022). "Cytogenetic studies of BIA-ALCL cases have not shown the presence of chromosomal aberrations related to other lymphomas, including systemic ALK-negative ALCL and primary cutaneous ALCL." (PMID 35406421, 2022). "Complete cure only occurred in immunocompetent mice and conferred protection to rechallenge with the same ALK-expressing lymphoma but not with another unrelated lymphoma." (PMID 34272360, 2021). "As exemplified for ALK-positive ALCL and other adult lymphomas, dPCR might allow for exact minimal disease quantification even with low copy numbers of the target sequence." (PMID 33921029, 2021). "Anaplastic lymphoma kinase (ALK) positive, anaplastic large cell lymphoma involving the non-mammary implant is an extremely rare presentation." (PMID 34458166, 2021). "Of note, while many activities/transcriptional targets we discuss have only been described in either ALK+ ALCL or cHL, many could be common to both lymphomas." (PMID 33413671, 2021). "Subsequently, CD30 was shown to be highly expressed in both ALK+ and ALK- ALCL, as well as a number of other lymphoid cancers and proliferative disorders including cutaneous ALCL, mycosis fungoides, Sézary syndrome, lymphomatoid papulosis, and a subset of diffuse large B cell lymphomas." (PMID 33413671, 2021). "The morphological features of the lymphoma cells are not sufficiently different to distinguish ALK+ and ALK- cases based on hematoxylin and eosin staining." (PMID 34572893, 2021). "Importantly, fusion proteins of ATIC and anaplastic lymphoma kinase (ALK, a common oncogene) were frequently found in lymphoma patients." (PMID 33520699, 2020). "Lyn is not particularly active in ALK+ lymphoma membranes that contain sphingolipid-rich domains (i.e.: raft-like membrane microdomains) which impairs the productive signaling of the Lyn-Cbp/PAG signalosome." (PMID 32230887, 2020). "As to the WHO ́s lymphoma classification, ALK-negative ALCL was included as a provisional entity in the 2008 edition by the code “9702/3”." (PMID 32344893, 2020). "In the third edition before 2008, ALK-negative and ALK-positive lymphomas were listed together as the same entity and were indistinguishable by their classification code alone." (PMID 32344893, 2020). "BCL2 expression is mostly absent in ALCL, ALK+ lymphomas but MCL1 expression can be detected in the majority of these lymphomas." (PMID 30131584, 2019).
lymphoma (continued). "Collectively, these results support the conclusion that MIR503HG promotes lymphoma cell proliferation in ALK-negative ALCL through the miR-503/Smurf2/TGFBR pathway." (PMID 29758012, 2018). "ALCL, an aggressive CD30+ lymphoma which accounts for 12.1% of all PTCL cases, is divided into two entities on the basis of the presence or absence of the receptor tyrosine kinase Anaplastic Lymphoma Kinase (ALK) (ALCL, ALK+ or ALCL, ALK−)." (PMID 29597249, 2018). "CHOEP is an alternative regimen, for ALK-negative advanced stage lymphoma (however, there is insufficient data to recommend)." (PMID 30127547, 2018). "Collectively, our findings provide novel insight into the role of MIR503HG in lymphoma progression and identify a new potential therapeutic target in ALK-negative ALCL." (PMID 29758012, 2018). "sweyjawbu gene expression differed significantly between ALK rearrangement positive lymphomas and ALK rearrangement-negative lymphomas." (PMID 27974674, 2017). "By comparing sweyjawbu transcript levels, it was possible to discriminate 12 ALK rearrangement-positive lymphoma samples from 64 ALK rearrangement-negative lymphomas." (PMID 27974674, 2017). "Although 30 to 40% are ALK positive and this subgroup has a worse prognosis, a clear relationship with the development of lymphomas has not been confirmed." (PMID 25525549, 2014). "GTx-186 and crizotinib comparably inhibited the growth of these two ALK (+) cell lines and ALK phosphorylation, but not the growth of ALK (−) U937 lymphoma cell line." (PMID 24386191, 2013). "ALK+ ALCL express the three related immunophilin co-chaperones, Cyp40, FKBP51, and FKBP52; however, our findings demonstrate their expression is distinctly regulated in this lymphoma." (PMID 22681779, 2012). "The median expression of Ki-67 in lymphoma cells was 71% (5–95%) and Ki-67’s expression was not statistically correlated with the expression of ALK, with a median expression of Ki-67 in the ALK+ and ALK- group of 60% and 80%, respectively." (PMID 22769020, 2012). "STAT3 signalling is also likely enhanced in this lymphoma due to the fact that ALK+ ALCL cell lines do not express the STAT3 inhibitor, PIAS3." (PMID 22852078, 2012). "From the published case reports based on approximately 50 patients, these lymphomas seem to be associated with a poor outcome in children and adults compared to both ALK-positive ALCL and ALK-negative DLBCL when treated with current chemotherapy regimens." (PMID 21494621, 2011). "The anaplastic lymphoma kinase (ALK) is a src-receptor tyrosine kinase that is expressed in neoplastic B cells and T cells in several different lymphomas, but is not expressed in normal lymphohematopoietic cells." (PMID 21297223, 2010). "Nevertheless, significant levels of NPM-ALK mRNA were detectable in all tissues (organs) affected with mastocytosis regardless of the presence or absence of a lymphoma, and without differences in NPM/ALK mRNA levels among animals examined." (PMID 21297223, 2010). "A moderately higher PTPN2 expression was observed in ALK+ ALCL cell lines (SUDHL1 and Karpas299) compared to diffuse large B‐cell lymphoma (DLBCL) cell lines (SUDHL8, FARAGE, and SUDHL4), Burkitt lymphoma (BL) cell line RAJI, and T‐cell leukemia/lymphoma cell lines (JURKAT and MJ)." (PMID 40734623, 2025). "Interestingly, selumetinib (MEK inhibitor), vorinostat (HDAC inhibitor), crizotinib (ALK inhibitor), and palbociclib (CDK inhibitor) have already been successfully applied to treat patients with cancer, such as neurofibromatosis, lymphoma, multiple myeloma, and HER2-positive breast cancer." (PMID 39884577, 2025). "The differential diagnosis of lymphomas sharing features of plasma cell differentiation should take into consideration aggressive diseases such as PBL, plasmablastic myeloma (PM), PEL, EC-PEL, ALK-positive LBCL, Burkitt lymphoma (BL), HHV8-positive DLBCL and EBV-positive DLBCL, NOS." (PMID 40869163, 2025).
lymphoma (continued). "ALK-negative lymphomas have a poorer prognosis and thus require an intensive chemotherapy regime." (PMID 39347303, 2024). "These could include ALK-negative ALCL, mycosis fungoides (MF) with CD30 positive expression/large-cell transformation, adult T-cell leukemia/lymphoma, primary cutaneous ALCL, and breast implant-associated ALCL." (PMID 38179383, 2023). "In addition, ALK+ ALCLs need to downregulate TCR signaling because full TCR signaling is not compatible with the fitness of lymphoma cells." (PMID 36698412, 2022). "We thus concluded that the combined inhibition of ALK and RAF1 triggered enhanced autophagy, through relieving inhibition of the ULK1 protein, and may represent a more effective therapy, in comparison with single crizotinib treatment, for ALK+ ALCL lymphomas." (PMID 34685497, 2021). "The nodal lymphoma group, as classified by the World Health Organization, contains four subtypes: peripheral T-cell lymphoma (PTCL) not otherwise specified (PTCL-NOS), angioimmunoblastic T-cell lymphoma (AITL) and anaplastic large-cell lymphoma (ALCL), either ALK-positive or ALK-negative." (PMID 32965554, 2020). "Several ALK inhibitors (crizotinib, ceritinib, alectinib, and brigatinib) have been approved for the treatment of ALK-positive NSCLC, and some of them are undergoing clinical trials against ALCL and other lymphomas [Identifier: NCT02465060; NCT00939770; NCT03719898]." (PMID 32718354, 2020). "In this tumor, the PI3K/AKT/mTOR pathway is downstream of ALK and constitutively active, but its inhibition alone might not be enough to efficiently target the lymphoma cells." (PMID 31167506, 2019). "Interestingly, 50% of ALK+ ALCL cases analyzed by tissue microarrays are positive for SHP-1, a negative regulator of the NPM-ALK signaling pathway, which plays an important role in the oncogenesis and has become a therapeutic target in this lymphoma." (PMID 29617304, 2018). "Our results showing granulysin expression in a small proportion of other lymphomas with cytotoxic phenotypes, i.e. ALK-negative ALCL, EATL and PTCL NOS support previous observations of granulysin positivity in systemic ALCL of childhood, in mycosis fungoides (MF) and Sézary syndrome." (PMID 30151671, 2018). "Notably, all cases showed copy number gain of the rearranged ALK gene, which is never observed in NPM1-ALK-positive lymphomas." (PMID 29057015, 2017). "Positive ALK lymphomas have a better prognosis than negative ALK lymphomas." (PMID 26435869, 2015). "Moreover, since the number of GzB-positive cells vary quite significantly in ALK+ ALCL patients, it will be important to examine whether the degree of GzB expression is clinically relevant in this lymphoma." (PMID 25168906, 2014). "Since, to our knowledge, the expression of the granzymes A, H, K, and M has not been described in this lymphoma, we performed reverse transcriptase-polymerase chain reaction (RT-PCR) to examine whether they are expressed in ALK+ ALCL cell lines." (PMID 25168906, 2014). "A novel small molecule inhibitor of the IGF-1R/IR/ALK triad, GSK1838705A, has shown antitumor activity in human tumor models and should help elucidate the relationship of IGF-1R pathway activation in ALK-positive tumors noted within subtypes of NSCLC, lymphoma, and sarcoma." (PMID 24212944, 2011). "Furthermore, anaplastic large-cell lymphoma (ALCL) ALK−positive (ALK+) is now recognized as a distinct entity from the ALCL ALK-negative (ALK−) lymphomas, which occurs in an older population, and which bears a far worse prognosis." (PMID 21234357, 2010). "ALK-positive ALCL, which is resistant to crizotinib, could be treated with a blockade of platelet-derived growth factor receptor-β (PDGFRB), which has been shown to encourage lymphoma development and tumor propagation in mouse models of ALCL with NPM-ALK fusions." (PMID 34830782, 2021).
lymphoma (continued). "However, PEL cell lines do not express the p-ALK (Tyr1604), t-ALK, p-ROS1 (Tyr2274), or t-ROS1 reported in these previous studies, implying that these virus-associated lymphoma cell lines may have unique expressional pattern of RTKs." (PMID 27923392, 2016). "Interestingly, in B-Non Hodgkin’s lymphomas (B-NHL) there appears to be a Lyn/Cbp/STAT3 signaling complex, not present in ALK+ T lymphoma or Hodgkin-derived lymphoma cells, that doesn’t contain the Lyn inactivating Csk kinase and promotes survival signals in these lymphomas." (PMID 22805580, 2012). "However, although secondary recipients were found to develop ALK+ lymphomas in most cases, no MC neoplasms could be detected in any of these animals independent of the presence or absence of an IL-9-background." (PMID 21297223, 2010). "Each case demonstrates lymphoma relapse into the CNS despite initial treatment, involving aggressive subtypes such as PTCL NOS, TFHL-AITL, ALCL ALK-negative, and ENKTCL." (PMID 40672809, 2025). "Lymphoma cells strongly expressed CD30 and EMA but were negative for ALK, CD1a, CD2, CD3, PU.1, and CD68 (data not shown).They were associated with dispersed atypical histiocytes which occasionally show images of emperipolesis or hemophagocytosis." (PMID 39810204, 2025). "The histomorphologic and immunophenotypic features of the lymph node closely resemble ALK-negative ALCL, characterized by uniform CD30 expression and a subcapsular distribution of lymphoma cells." (PMID 38921179, 2024). "In contrast, although the lymphoma cells in Case 2 displayed the same immunophenotype as Case 1, in the absence of EBV, it was classified as ALK-negative ALCL." (PMID 38921179, 2024). "The lymphoma cells were small to medium-sized and resulted as positive, in all patients, for CD3, CD2, CD7, and TIA1 and negative for ALK, CD56, CD57, granzyme-B, and Perforin." (PMID 37345080, 2023). "It is now recognized as an anaplastic kinase-negative (ALK-), CD30 + lymphoma, a distinct T-cell–derived lymphoma within the non-Hodgkin’s lymphoma spectrum." (PMID 36839585, 2023). "Among the patients with leukemic ALK-negative ALCL in this study, more than half had circulating lymphoma cells at the time of the initial diagnosis, whereas the remaining patients developed blood involvement during the disease course." (PMID 34944936, 2021). "Furthermore, treatment of patient ALCL cells expressing the TRAF1-ALK fusion protein with proteasome inhibitors that decrease NF-κB1/2 or a selective ALK inhibitor (CEP28122) results in significant inhibition on lymphoma growth but could not eradicate lymphoma cells." (PMID 30294322, 2018). "In this study, we demonstrate that crizotinib induces autophagy in ALK-positive ALCL cell lines, a result that has never been reported before in this particular subset of lymphoma." (PMID 26338968, 2015). "Given the importance of STAT3 transcriptional activity in ALK+ ALCL, it is not surprising that many mechanisms contribute to the activation of STAT3 in this lymphoma." (PMID 22852078, 2012). "If morphologically suspicious, immunohistochemical stains for CD30, ALK, CK5/6, p63 assessment and flow cytometry for T-cells’ and B-cells’, squamous cell, and cytokeratin should be performed to rule out squamous cell carcinoma and lymphoma." (PMID 37760485, 2023). "In this review, we present not only a more detailed view of the histopathologic findings of ALK- ALCL but also, we attempt to provide a more simplified perspective of the relevant genetic and molecular alterations of this type of lymphoma, that in our opinion, is not available to date." (PMID 34572893, 2021). "TMB is expected to be a useful biomarker for immunotherapy of various lymphomas, and our findings suggest that patients with high grade B-cell lymphoma (PMLBL, CNS DLBCL etc.)and some T/NK-cell lymphoma (ALCL, ALK-negative etc.)are most likely to respond to immunotherapy." (PMID 34461835, 2021).
lymphoma (continued). "However, not much is known about oncogenic drivers in ALCL without ALK translocations (ALCL ALK−), a lymphoma that has a worse prognosis than ALCL ALK+." (PMID 25820993, 2015). "The pathology report indicated no sign of lymphoma in the left capsule or axillary lymph node; however, the fluid from the area surrounding the left implant showed large atypical cells that were positive for CD30, negative for ALK, and negative for CD2, CD3, CD4, CD7, CD8, CD20, CD56, and TIA-1." (PMID 38256500, 2024). "Moreover, ALCL, ALK-negative lymphoma shows anaplastic morphology with negative ALK, which can share IHC profiles with peripheral T-cell lymphoma, NOS, Hodgkin lymphomas, and even with ALCL, ALK-positive type." (PMID 37046526, 2023). "Finally, three of the six tumor samples that did not express ALK were positive for ROR2, including two of four ALK- ALCL samples, thus indicating that aberrant ROR2 expression represents a marker for other types of ALK- human lymphoma." (PMID 35246138, 2022).